TNF (tumor necrosis factor)
Diseases named in the same sentence as TNF in open-access papers (continued):
Sharing a sentence is not in itself a finding about the gene and the disease.
Granuloma (continued). "Thus, TNF inhibitors may prevent granuloma pathogenesis by binding to TNF‐alpha and inhibiting its activity." (PMID 38903487, 2024). "However, due to the lower levels of TNF-α found in the groups challenged with vEVs compared to control EVs, it is possible that these EVs are capable of modulating the formation of coalescent granulomas in new infections." (PMID 38511558, 2024). "A stronger piece of clinical evidence that granulomas serve a host-protective function is that individuals with severe immunodeficiency (such as those with AIDS or immune suppression by pharmacologic TNF blocking agents) are highly susceptible to Mtb and have poorly-formed or absent granulomas." (PMID 39717773, 2024). "Previously, in our group, a C57BL/6J Nos2–/– mouse model presenting granuloma that includes central necrosis, hypoxia, and caseation has been established with an intradermal M. tuberculosis infection and transitory blocking of tumor necrosis factor alpha (TNF-α) function (37, –, 39)." (PMID 34311585, 2021). "SEA is known to induce the expression of TNF, therefore, we reason that it might be only after granuloma initiation, at which point significant numbers of macrophages are in contact with the egg, that TNF is produced above the threshold to induce these chemokines." (PMID 33465071, 2021). "Increasing TNF-α levels, may be associated with the increased presence of necrosis within granulomas as they progress from stage I, non-necrotizing granulomas to stage IV granulomas with significant necrosis." (PMID 34026898, 2021). "TNF-α signaling is complex, and the cytokine serves multiple functions, including in the formation and maintenance of granulomas, as evidenced by the observation that mice deficient in TNF-α or receiving anti-TNF-α therapy produce defective granulomas following mycobacterial infection." (PMID 33552087, 2020). "Furthermore, increased utilization of oleic and palmitic acid by the Mtb from anti-TNFα mAb treated granulomas as compared to that of the Mtb from the control IgG treated granulomas also demonstrate that the Mtb is metabolically active following anti-TNFα monoclonal antibody treatment." (PMID 23308269, 2013). "Auramine-O and Nile red staining of WT Mtb cells from granulomas treated with the control IgG, showed that majority of the cells were positive for Nile red and that most of the WT Mtb cells from granulomas treated with anti-TNFα mAb were positive for the Auramine-O stain." (PMID 23308269, 2013). "IL-22 has been suggested to play a protective role in the disease by inhibiting CD4+ T cell migration and collagen deposition and the decrease in IL-22 in the TLR2/9-/- mice may explain the development of granulomas despite decreased T cell activation and TNFα production in these mice." (PMID 24023674, 2013). "In addition, TNF-α was highly correlated with the number of large granulomas (r = 0.85, p<0.0001)." (PMID 22457760, 2012). "Moreover, granulomas have the ability to secrete the inflammatory cytokines IL-6 and TNFα." (PMID 16542426, 2006). "Increased expression of TNF, IFN-γ and IFN-γ RNA, as well as TNF-inducible chemokines CXCL9, CXCL10, and CXCL11, which are CXCR3 ligands, was shown in granuloma." (PMID 40427602, 2025). "Immunological analysis of the supernatant from these infected cells revealed the presence of several cytokines involved in human granuloma formation, including IL-6, IL-8, IFN-γ and TNFα." (PMID 40406522, 2025). "Instead, the proportion of CD8α− γδ T cells in granulomas increased and had similar function as CD8α+ γδ T cells, thereby replacing production of IFN-γ, TNF, IL-2, and/or IL-17." (PMID 39912921, 2025). "It was observed that the center of granulomas has a proinflammatory milieu with the abundance of LTA4H and TNF-α, ROS mediators alongside antimicrobial effectors like cathelicidin along with proinflammatory eicosanoids." (PMID 40406522, 2025).
Granuloma (continued). "Tumor necrosis factor (TNF) and INF-γ are the main cytokines that contribute to the formation of granulomas, and these cytokines simultaneously play a key role in the pro-inflammatory immunomodulation of the response against SARS-CoV-2." (PMID 39100065, 2024). "In this study, higher immunolabeling of IFN-γ, TNF-α, and iNOS with fewer TGF-β was observed in granulomas from calves compared with adult cattle, suggesting a greater proinflammatory response." (PMID 37180066, 2023). "Although proinflammatory cytokines have been associated with mycobacterium infection control, we observed more immunolabeling of IFN -γ, iNOS, and TNF-α and less TGF-β in the calf granulomas compared to adult granulomas." (PMID 37180066, 2023). "Everolimus treatment at 1 and 2 nM significantly reduced the levels of TNF-α compared to the control group, as did INH plus 2 nM everolimus compared to M. tb-containing in vitro granulomas only treated with INH." (PMID 37998388, 2023). "In the acute stages of granuloma development, they exhibit a highly polarized expression of T helper Type 1 (Th1) cytokines, including interferon-gamma (IFN-γ) and tumor necrosis factor-alpha (TNF-α), along with evidence of Th17 cell signaling." (PMID 38202021, 2023). "The immunolabeling quantification showed that granulomas from calves had more mycobacteria, CD3+ cells, IFN-γ, TNF-α, and inducible nitric oxide synthase (iNOS) than those of adult cattle." (PMID 37180066, 2023). "The mechanism of action of this drug group is based on their rapid and potent anti-inflammatory activity as a result of suppression of cytokines (including TNF-α, INF-γ) that contribute to the development of granulomas." (PMID 36148463, 2022). "Additionally, while C57BL/6 mice fail to form necrotic granulomas, disseminated infection in C57BL/6 mice deficient for the critical IFN-γ-induced factor iNOS resulted in the formation of sporadic necrotic granulomas that could be enhanced by neutralization of either IFN-γ or TNF." (PMID 35320930, 2022). "The TNF-α+ immunohistochemical staining showed higher TNF-α+ response in BCG vaccinated as compared to the level of response in non-vaccinated calves, and that was the case in all four stages of granuloma (P < 0.05)." (PMID 34604367, 2021). "The parenchymal architecture of the lungs of P10+DODAB-treated animals was largely preserved with only a few granulomas present, and tissue cytokine analysis showed a Th1 cytokine profile with augmented levels of IL-12, IFN-γ and TNF-α, and low levels of IL-4." (PMID 34073466, 2021). "The role of GM-CSF, IFN-γ, TNF-α, IL-10 and TGF-β in the generation of multinucleated giant cells, that are characteristically present in granulomas was studied, stimulating human monocytes with Paracoccidioides antigen in an in vitro setting." (PMID 33668671, 2021). "The granuloma model demonstrated a Th1 cytokine profile with increased secretion of IL-2R, IL-7, IL-12, IFN-γ, and TNF-α." (PMID 32350353, 2020). "Their study demonstrated the possible involvement of RANKL, TNF-α, IL-33, cathepsin K, and OPG in the development of radicular cysts and periapical granulomas, with emphasis on the highest immunoreactivity of cathepsin in cysts and TNF-α and OPG in granulomas." (PMID 31011287, 2019). "When the granulomas were treated with PZA, there was a general upwards trend in TNF-α production from the BCG vaccinated categories, especially in the lower concentrations." (PMID 31569759, 2019). "In granuloma, PEA reduced inflammatory hallmarks, including tumor necrosis factor (TNF)-α and granuloma-dependent angiogenesis." (PMID 31878942, 2019). "The addition of L-GSH to granulomas from BCG-vaccinated subjects lead to increased CD4 T cell viability, increased TNF-α and IFN-γ production, decreased PD-1 expression, and diminished T cell exhaustion." (PMID 31569759, 2019).
Granuloma (continued). "Previous work on granulomas emphasized the role of T-helper cell type 1 (Th1) immunity, CD4 T cells, IFN-γ signaling, IL-12, tumor necrosis factor (TNF)-α, eicosanoid signaling, and lipid dysregulation." (PMID 30694692, 2019). "Of note, LNs with granulomas that are sterile had significantly higher frequencies of CD3+ T cells producing IFNγ; CD8+ cytotoxic T cells producing IFNγ, IL-2 or TNF and CD20+ B cells producing IL-2 than CFU+ LNs." (PMID 30383808, 2018). "Nevertheless, CFU- LNs with granulomas had significantly higher proportions of CD11b+ cells producing IL-10 when compared with CFU+ LNs with granulomas, while CD4+ T cells producing TNF were significantly higher in CFU+ LNs." (PMID 30383808, 2018). "Treatment of granulomas from T2DM subjects with RIF+NAC resulted in a significant decrease in the levels of IFN-γ and TNF-α, and a significant increase in the levels of IL-10." (PMID 30258443, 2018). "TNF, IL-1β, IL-18, IL-1RA, IL-8, MCP-1, and MIG were all present at significantly (p<0.05–0.0001) lower levels in secondary granulomas, with a trend towards lower IFN-γ." (PMID 30312351, 2018). "In particular, an accelerated mortality rate, poorly organized lung granuloma-lesions and increased IFN-γ and TNF-α expression as signs of the worsening outcome have been reported in Tat transgenic mice." (PMID 27549342, 2016). "For example, TNF neutralization led to dynamic granulomas (increasing in size or FDG avidity), but this was restricted to a subset of granulomas in reactivating monkeys." (PMID 27379816, 2016). "TNF-α and IFN-γ are particularly important in promoting the formation and function of the granulomas, whereas IL-10 is one of the main negative regulators of the response in both sarcoidosis and TB." (PMID 28127112, 2016). "In fact, knockout of SK1 prevented formation of granulomas by reducing the amount of S1P in the bronchoalveolar lavage fluid which resulted in lowered levels of MCP-1 and TNF-α." (PMID 26688618, 2015). "Granuloma formation in the liver in response to Leishmania requires the recruitment of CD4+ T cells and the release of IL-12, IFNγ and TNF, among other cytokines." (PMID 26684322, 2015). "Nevertheless, sterile granulomas had modestly higher TNF (p = 0.0091), IL-17 (p = 0.0344) and T-1/T-17 (CD3+ T cells producing single or combinations of IFN-γ, IL-2, TNF, or IL-17 cytokines) (p = 0.0273) cytokine producing T cells than non-sterile granulomas." (PMID 25611466, 2015). "Five weeks after infection, a very high level of TNF-α was observed in the lungs of saline-treated mice; TNF-α staining was extensive in necrotic areas within the advanced coalescent granulomas." (PMID 25152895, 2014). "As the pathological role of TNF-α has become better understood, the physiological role of TNF-α in maintaining the latency of TB in granulomas in infected people has also been better clarified." (PMID 25317081, 2014). "A second mechanism in sarcoidosis is that granulomas are characterized by local proinflammatory activated CD4 + T lymphocytes with Th1 profile (IFNγ, IL2) stimulating TNFα production by macrophages." (PMID 24373564, 2013). "Continuous cigarette smoke exposure locally, by not systemically, impairs APC accumulation and their production of TNF, IL-12, and RANTES, blunts the recruitment of CD4+IFN-γ+ T cells to the lung, and weakens the formation of granuloma." (PMID 23527127, 2013). "Overall, the number of granulomas was highly correlated with mRNA induction of IFN-γ (r = 0.82, p<0.0001) and TNF-α (r = 0.83, p<0.0001)." (PMID 22457760, 2012). "Tumor necrosis factor alpha (TNF-α) is a cytokine that plays a central role in the host responses against TB, including formation of granulomas and containment of disease." (PMID 22761866, 2012).
Granuloma (continued). "TNFα neutralizing agents in animal models following bacillus Calmette-Guérin (BCG) vaccination and in LTBI individuals (102, –, 107) have shown worsening disease, dissolution of granulomas, Mtb dissemination, and reactivation of TB." (PMID 39918314, 2025). "Interestingly, TNF, WNT, CD6, APRIL, EPHA, and SEMA6 signaling pathways were reduced in Mtb granulomas compared to MAH granulomas." (PMID 41586350, 2025). "Furthermore, these APCs trigger an exaggerated Th1 immune response, which produces high levels of Tumor Necrosis Factor alpha (TNF-α) and secrete interleukins 12, 15, and 18, leading to persistent granuloma and chronic inflammation." (PMID 40078389, 2025). "TNF is essential for the early induction of chemokines (e.g., CCL2, CCL3, CCL4, CXCL9–11) and for proper spatial organization of macrophages and lymphocytes in granulomas, thereby creating a protective pulmonary microenvironment." (PMID 40427602, 2025). "One such shared feature is the persistent activation of Th1 and Th17 cells, which in sarcoidosis occurs within granulomas and leads to elevated production of IFN-γ, IL-17, and TNF-α, further amplifying macrophage activation and sustaining the granulomatous response." (PMID 40837573, 2025). "While 2 doses of anti-TNFα had little obvious effect on pyogranuloma formation (data not shown) the role of TNFα in granuloma formation is well-supported." (PMID 38404573, 2024). "Moreover, as shown for paradoxical skin reactions, anti-TNF-α can increase INF production, which is crucial for granuloma formation." (PMID 37175894, 2023). "It has been shown that the mechanisms of action of ETA and IFX can produce different TNF-α concentrations in the tissue, and higher levels of biologically active TNF-α from ETA therapy may foster the formation of granulomas." (PMID 37175894, 2023). "Different studies reported that, upon in vitro stimulation, there is an increase of IFN-γ and TNF-α produced by immature CD56bright NK cells in BALF of sarcoidosis patients, and this may suggest the involvement of NK cells in granuloma formation." (PMID 36685602, 2022). "Granuloma stage did have modest positive and negative correlations with TNF-α and IL-10, respectively." (PMID 34026898, 2021). "The vaccinated and infected mice showed the increased expression of TNF-α, IFN-γ, and IL-6 following expression of the anti-inflammatory genes IL-10 and TGF-β in the liver, justifying the reduction in the number and size of the observed granulomas." (PMID 34992597, 2021). "TNF-α plays a significant role in the formation and maintenance of the sarcoidosis granuloma, and it is therefore not surprising that TNF-α antagonist drugs are effective anti-sarcoidosis agents." (PMID 34203188, 2021). "Furthermore, inflammatory cytokines, which present high levels at the beginning of granuloma formation, such as IFN-ɣ, IL-2, IL-4, MCP-1, and TNF-α, are important factors in reducing the spread of the bacteria." (PMID 34843474, 2021). "This is consistent with our prior reactivation studies in which a subset of newly developed granulomas had no culturable Mtb during reactivation after TNF neutralization." (PMID 32730321, 2020). "In TNF-neutralized macaques, early signs of reactivation (i.e., non-necrotizing granuloma formation adjacent to established and often mineralized granulomas) were observed microscopically in the lymph nodes." (PMID 32790739, 2020). "Mice infected with a strain of M. tuberculosis disrupted in the mce1 operon are unable to mount a strong pro-inflammatory response against WT Mtb, as evidenced by decreased levels of IL-6 and TNF-α; consequently, these animals do not form organized granulomas." (PMID 32973761, 2020). "Previous studies demonstrated a fine-tuning of TNF-α production in the host during TB infection, which allowed mycobacterial persistence in granulomas without apparent disease (LTBI status) (18, 32, –, 34)." (PMID 31992621, 2020).
Granuloma (continued). "We found that TNF release decreased in PBMCs from patients unable to form granulomas with no increase in IL-10, suggesting that the modulation of TNF production was not related to the overproduction of IL-10." (PMID 32411623, 2020). "In addition to TNF-α or IFN-γ, IL-17a contributes to the formation of granulomas against mycobacterial infection." (PMID 33273606, 2020). "TNF-α and IFN-γ levels were measured in the supernatants of INH-treated granulomas." (PMID 31569759, 2019). "Macrophages in the alveoli secrete a large number of interleukin-1 (IL-1), interleukin-6 (IL-6), tumor necrosis factor-α (TNF-α), and other cytokines, so that lymphocytes and monocytes are accumulated in mycobacterial invasion sites and followed by granulomas formation." (PMID 31921874, 2019). "Spatial studies combining mass spectrometry with confocal microscopy of dissected human tuberculous granulomas show that necrotic tuberculous granulomas are enriched for LTA4H and TNF as compared to nonnecrotic granulomas from the same lung." (PMID 31474371, 2019). "Tumor Necrosis Factor-α (TNF-α) is a crucial cytokine in the inflammatory cascade by activating the type 1 T helper (Th1) immune response, enhancing the activity of the macrophages and essential for the formation and maintenance of granulomas." (PMID 31469834, 2019). "The granuloma index was not affected by TNF-α blockade in the active disease group, but significantly reduced the levels of IFN-γ, IL-12p40, IL-17 and IL-10 in all antigenic stimulus conditions tested." (PMID 29543912, 2018). "TNF-α acts in synergy with IFN-γ in the stimulation of nitric oxide (NO) production by macrophages, besides being a key cytokine in the formation and maintenance of granulomas." (PMID 29543912, 2018). "Increase IFNγ & TNF-α levels and PMN cells & functions.Increase T helper CD4 T cells & CD8 T cells activity.Improve Ag- specific antibody response.Restored DTH response and Granuloma formation.Reduced IL-6 cytokine and bacterial load." (PMID 30534129, 2018). "The immune response of TT patients is characterized by a Th1 cytokine response (interferon gamma [IFN-γ], interleukin (IL)-2, IL-15, and tumor necrosis factor [TNF]), vigorous T-cell responses to M. leprae antigens, and containment of the bacilli in well-formed granulomas." (PMID 28162092, 2017). "The host cellular immune response starts with the secretion of cytokines, such as interleukin 12 (IL-12) and tumor necrosis factor alpha (TNF-α), and chemokines that recruit the immune cells to the site of infection to form a compact cluster of immune cells, known as a granuloma." (PMID 34993126, 2017). "TNF−/− and etanercept-treated groups showed a higher number of granulomas, although not significantly (data not shown)." (PMID 29184553, 2017). "First, we added recombinant TNF to PBMCs from 3 patients who did not form granulomas: TNF was unable to increase the formation of immune and innate granulomas." (PMID 27441846, 2016). "Animals that would develop reactivation had a higher proportion of FDG avid (defined as SUV ≥ 5) granulomas (67.2%) compared to non-reactivator animals (30.8%) (Fisher’s Exact, p<0.0001) before TNF neutralization." (PMID 27379816, 2016). "Taken together, these results showed that the formation of granulomas was not directly related to TNF." (PMID 27441846, 2016). "TNF-α plays a significant role in antigen-stimulated, cell-mediated immune responses and in the development of non-caseating granulomas in a variety of diseases." (PMID 25866481, 2015). "Tumor necrosis factor-alpha (TNF-α) is a potent proinflammatory cytokine that is expressed by macrophages and T cells and is considered essential for the formation and maintenance of granuloma." (PMID 26273486, 2015).